P4HA2 (prolyl 4-hydroxylase subunit alpha 2)
Diseases named in the same sentence as P4HA2 in open-access papers (continued):
Sharing a sentence is not in itself a finding about the gene and the disease.
tumor (continued). "Moreover, we also detected decreased Ki67 expression in the tumor tissues obtained from P4HA2 knockdown group mice compared with those from the negative control group." (PMID 32226497, 2020). "In addition, we also demonstrated that P4HA2 knockdown suppressed EMT process and tumor metastasis." (PMID 32226497, 2020). "Notably, higher P4HA3 expression was reported in the stroma than in tumor regions, which was not seen with P4HA1 and P4HA2 expression." (PMID 39716322, 2024).
cancer (40 papers, 2011 to 2026). A tumor composed of atypical neoplastic, often pleomorphic cells that invade other tissues. "In univariate COX analysis across multiple cohorts, P4HA2 was a risk factor for most cancers but potentially a protective factor in DLBC." (PMID 41424847, 2026). "An integrative analysis of multiple mRNA-seq datasets from Gene Expression Omnibus and The Cancer Genome Atlas reveals a crucial gene, prolyl 4-hydroxylase subunit alpha-2 (P4HA2), implicated in PTC progression." (PMID 40379610, 2025). "In view of this, DARS and P4HA2 show potentially stronger cancer-driving properties at a higher mutation frequency." (PMID 35111402, 2022). "We also demonstrate that loss of RASSF1A and increased P4HA2 activity are associated with dissemination of cancer cells, which is in line with previous observations relating stiffness and metastasis." (PMID 31268606, 2019). "However, there was little association between P4HA2 expression levels in cancer tissues and patients' gender, age, or smoking history." (PMID 38951593, 2024). "Moreover, P4HA2 positively correlated with endothelia cells (r = 0.299, P = 3.87e-07) and cancer associated fibroblast (CAF) cells (r = 0.35, P = 2.10e-09)." (PMID 34249930, 2021). "We conducted in-depth exploration of P4HA2 at the transcriptomic, proteomic, and genomic levels across pan-cancer datasets." (PMID 41424847, 2026). "To explore the mechanisms underlying this inhibitory effect of P4HA2 on STAT1, we investigated signaling pathways significantly associated with cancer via STAT1." (PMID 40406250, 2025). "Altogether, these results highlight P4HA2 as a conserved marker of the dormant state in cancer cells." (PMID 40671813, 2025). "We propose that P4HA2 promotes the proliferation and migration of cancer cells by binding to and inhibiting the function of the tumor suppressor protein STAT1." (PMID 40406250, 2025). "Our data indicate that P4HA2 increases the expression of PD-L1 by binding to and downregulating STAT1 expression, thereby increasing the risk of cancer." (PMID 40406250, 2025). "P4HA2 is activated by the hypoxia-inducible factor 1 (HIF-1) under hypoxic conditions, causing extracellular matrix remodeling and promoting cancer metastasis." (PMID 40379610, 2025). "The findings of our study indicate that P4HA2 overexpression in HNSCC increased PI3K/AKT phosphorylation, which suggests that the PI3K/AKT axis contributes to the cancer-promoting impacts of P4HA2 overexpression in HNSCC." (PMID 38777998, 2024). "Various databases, including TCGA, TIMER, UALCAN, GEPIA, and K-M plotter, along with paraffin-embedded samples, were used to ascertain P4HA2 expression in cancer and its correlation with clinicopathological features." (PMID 38951593, 2024). "In summary, our study reveals an undiscovered hydroxylation-regulatory mechanism by which P4HA2 directly activates mTOR kinase, providing insights for therapeutically targeting mTOR kinase-driven cancers." (PMID 38654109, 2024). "We investigated the single nucleotide variations (SNVs) of HFRS genes in different cancers and observed that some genes (CCT6A, TF, KRT14, P4HA2, PGK1, SLC16A2, and STC2) were frequently mutated in COAD, STAD, UCEC, and SKCM." (PMID 36998462, 2023). "For example, knockdown of P4HA1 and P4HA2 in prostate and breast cancer, respectively, reduced cancer cell proliferation, invasion, and metastasis, both in vitro and in vivo." (PMID 35804902, 2022). "P4HA2, an essential enzyme during collagen formation, has been reported to be an indicator of many types of cancers progression." (PMID 33215860, 2021). "We first investigated the correlation between infiltration of immune cell subtypes and P4HA2 expression is based on the xCell across 33 cancers." (PMID 34249930, 2021). "Emerging studies have documented that prolyl-4-hydroxylase α subunit 2 (P4HA2) is involved in multiple processes of cancer progression." (PMID 32226497, 2020).
cancer (continued). "P4HA2 is thus emerging as a potential target for the development of novel therapeutic anti-cancer strategies." (PMID 32500033, 2020). "In the xenografted tumors both P4HA1 and P4HA2 mRNA are found at similar levels in cancer cells and in stroma, contrasting the stroma-specific expression of P4HA3." (PMID 27809802, 2016). "On the other hand, P4HA2 mRNA was detected at higher levels in the cancer cell compartment of all tumors but one." (PMID 27809802, 2016). "Our experimental results demonstrating that P4HA2 knockdown suppresses proliferation, and migration are consistent with previously reported findings that P4HA2-mediated collagen prolyl hydroxylation regulates cancer cell plasticity and migration." (PMID 41424847, 2026). "P4HA2 is markedly overexpressed across multiple cancer types, especially in BRCA." (PMID 41424847, 2026). "By analyzing differentially expressed miRNAs between GABPA-high and low tumors in the TCGA BLCA cohort, we observed that miR-30e was among the top ones that positively correlated with GABPA expression, while miR-30e has been shown to target P4HA2 in several cancer types." (PMID 40813762, 2025). "Similarly, IHC staining of tissue chips showed that the expression of P4HA2 in cancer tissues was higher than that in adjacent tissues." (PMID 39920992, 2025). "Conversely, P4HA2 overexpression exerts opposing effects on these cancer cell phenotypes." (PMID 40379610, 2025). "These concordant results highlight the critical role of P4HA2 in cancer progression." (PMID 38522060, 2024). "This controversy regarding the prognostic role of P4HA2 in cancer progression may be attributed to the different effects of collagen deposition in TME of several cancers." (PMID 38522060, 2024). "Moreover, we found that TPD52, TF, and CCT6A were more frequently heterozygous amplified while STC2, CISD1, and P4HA2 were more likely to occur in heterozygous deletion in cancers." (PMID 36998462, 2023). "Herein, the authors found that P4HA2 was positively related to these immune cells, suggesting that P4HA2 may be involved in the immune escape of cancer cells." (PMID 36403427, 2022). "The prolyl 4-hydroxylase subunit alpha-1/alpha-2 (P4HA1/P4HA2) catalyzes the post-translational modification of 4-hydroxyproline in the -Xaa-Pro-Gly- sequence in various collagens and has been shown to be an important regulator in various cancers." (PMID 36572937, 2022). "Finally, GSVA analysis found that DARS/GDI2/P4HA2/TRUB1 gene sets are closely related to the occurrence of cancer." (PMID 35111402, 2022). "Finally, we conducted a comprehensive evaluation of gene sets using GSVA and we found that the DARS/GDI2/P4HA2/TRUB1 gene sets are closely related to the occurrence of cancer." (PMID 35111402, 2022). "Thus, we selected P4HA2 to compare its RNA sequencing data with that in corresponding normal tissues across cancers in TCGA using TIMER." (PMID 34249930, 2021). "Knockdown of P4HA2 inhibited lipid droplets (LDs) accumulation and cancer cells invasion." (PMID 34249930, 2021). "Moreover, P4HA2 expression was significantly correlated with the immune score in 12 cancer types, mircroenvironment score in 14 cancer types, and stromal score in four cancer types (P < 0.0001)." (PMID 34249930, 2021). "The results indicated that P4HA2 was notably correlated with CD8+T cells in 11 cancer types, B cells and memory B cells in 12 cancer types, plasmacytoid dendritic cells and naïve CD4+ T cells in 13 cancer types, and CD4+Th1 cells in 17 cancer types (P < 0.0001)." (PMID 34249930, 2021). "Furthermore, P4HA2 expression was positively correlated with immune checkpoints in the majority of cancers." (PMID 34249930, 2021). "These concordant results emphasize the critical role of P4HA2 in cancer progression." (PMID 32226497, 2020). "Moreover, we highlight P4HA2 as a potential target for uncoupling ECM signals that support cancer stemness." (PMID 31268606, 2019).
cancer (continued). "Additionally, P4HA2 influences cancer cell behavior by enhancing collagen production." (PMID 38951593, 2024). "And most of the 24 DEPs (CDK1, SFN, PRKAR2B, MKI67 and MDK involved in the cell cycle; LOXL2, P4HA1, P4HA2, SPRX, DES, PRPH and CALML3 involved in construction and regulation of extracellular matrix; IL33 and EHD3 may involve in immune) were linked to cancer hallmarks." (PMID 33200655, 2020). "Altogether, these findings indicate that P4HA2 regulates autophagy activity to control the proteostasis of COL5A1, ultimately influencing the dormant state of cancer cells." (PMID 40671813, 2025). "DNA_REPAIR in the P4HA2 gene set and ANGIOGENESIS in the TRUB1 gene set are also two important mechanisms of cancer development." (PMID 35111402, 2022). "P4HA2 is a precursor of collagen and a metastasis marker and HOXB5 is a homeobox transcription factor whose overexpression has been found in several malignant tumors." (PMID 24548329, 2014). "The functions of two genes (P4HA2 and THBS2) in our signature of OSCC recurrence and their roles in cancer are not well understood." (PMID 21989116, 2011). "The mRNA expression levels of BNIP3L, C4orf3, and P4HA2 did not change statistically in the normal group and the cancer group." (PMID 41214670, 2025). "In this study, the results indicated that P4HA2 expression in OSCC tissues was significantly higher than in adjacent tissues, and P4HA2 expression in cancer tissues showed a negative correlation with the degree of differentiation in OSCC tissues." (PMID 38951593, 2024). "Prolyl 4-hydroxylase (P4H) activity is essential for maintenance of the collagen triple helix and P4HAs (P4HA1, P4HA2, P4HA3) plus P4HB are highly expressed in numerous tumors where they may contribute to cancer progression." (PMID 35846138, 2022). "P4HA2 as one of the subtypes of collagen prolyl-4-hydroxylases α isoforms, was activated by HIF-1 to inducing extracellular matrix remodeling under hypoxic conditions and promoting cancer metastasis." (PMID 34249930, 2021). "Interestingly, TCGA database analysis reveal higher levels of P4HA2 in HCC patients with a shorter overall survival and a higher cancer grade." (PMID 32500033, 2020). "To understand contributing factors that may be supporting NANOG activation and cancer stemness, we also checked β‐catenin and HIF‐1α as a known activator of P4HA2." (PMID 31268606, 2019). "HIF-1α induces the expression of P4HA1, P4HA2, PLOD1, and PLOD2 in different cancer and non-cancer cell lines, and enhanced activities of these enzymes are associated with increased collagen deposition in cancer tissue." (PMID 37490147, 2023).
P4HA2 also shares sentences with these, for which no sentence is quoted: breast invasive carcinoma (2 papers); cervical squamous cell carcinoma (2); cholangiocarcinoma (2); clear cell renal cell carcinoma (2); esophageal carcinoma (2); oral carcinoma (2); thyroid cancer (2); abortion (1); adenocarcinoma (1); asthma (1); atopic dermatitis (1); brain tumors (1); cervical tumor (1); Cirrhosis (1); colorectal adenocarcinoma (1); Crohn disease (1); Ductal Carcinoma (1); endometrial cancer (1); fibrosis (1); head and neck cancer (1); hearing loss (1); infection (1); juvenile idiopathic arthritis (1); lymphoma (1); paraganglioma (1); pheochromocytoma (1); soft tissue sarcoma (1); squamous cell carcinoma (1); stomach adenocarcinoma (1); urothelial bladder cancer (1).